EGR1 (early growth response 1)
Diseases named in the same sentence as EGR1 in open-access papers (continued):
Sharing a sentence is not in itself a finding about the gene and the disease.
gestational diabetes (1 paper, 2019). Carbohydrate intolerance first diagnosed during pregnancy. "EGR1 and NAMPT can be used as marker genes for childhood-onset T2D, and gestational diabetes and chronic inflammation are risk factors that lead to the development of childhood-onset T2D." (PMID 30755828, 2019). "The gene EGR1 promotes the development of gestational diabetes by adversely impacting the glucagon-controlled gluconeogenesis." (PMID 30755828, 2019).
glomerulosclerosis (1 paper, 2022). A hardening of the kidney glomerulus caused by scarring of the blood vessels. "EGR1 expression in podocytes was increased in mice with proteinuria, while the loss of EGR1 reduced proteinuria and glomerulosclerosis in mice." (PMID 34975320, 2022).
Glucose intolerance (1 paper, 2023). Glucose intolerance (GI) can be defined as dysglycemia that comprises both prediabetes and diabetes. "Impairment of the biological activity of Egr-1 and Elk-1 in pancreatic β-cells leads to glucose intolerance and dysregulation of glucose homeostasis, the process that maintains glucose concentration in the blood within a narrow range." (PMID 36614256, 2023).
hemorrhage (1 paper, 2025). Loss of blood from the vascular compartment to the exterior or into nonvascular body space as a result of rupture or severance of the blood vessels. "In conclusion, we reveal a distinct molecular mechanism by which SFTSV-induced sVEGFR1 release via upregulated EGR1 contributes to hemorrhage, suggesting that SFTSV infection disrupts the balance between the pro-angiogenic and anti-angiogenic state." (PMID 40789964, 2025). "Targeting the EGR1/sVEGFR1/hemorrhage axis may offer a therapeutic strategy to prevent hemorrhage in SFTSV infection." (PMID 40789964, 2025). "Thus, our findings suggest that the EGR1/sVEGFR1/ hemorrhage axis might be a potential target for the development of novel anti-hemorrhagic therapies during SFTSV infection." (PMID 40789964, 2025).
herpesvirus infections (1 paper, 2019). "EGR1 regulates viral gene expression in the context of other herpesvirus infections." (PMID 31725811, 2019).
hypertrophic obstructive cardiomyopathy (1 paper, 2023). "In addition, Egr1 and the proto-oncogene Fos are significantly downregulated in myocardia with hypertrophic obstructive cardiomyopathy compared to those in the control group." (PMID 36736425, 2023).
hypophosphatemia (1 paper, 2015). Lower than normal levels of phosphates in the circulating blood. "Blockade of ERK1/2 signaling in the kidney in Hyp mice is associated with reduction in egr-1 gene expression and improvements in the hypophosphatemia, 1,25(OH)2D deficiency and skeletal mineralization defects." (PMID 26588476, 2015). "To determine whether egr-1 mediates the hypophosphatemia induced by FGF23 in Hyp mice, we generated the double mutant Hyp/egr-1-/- mice." (PMID 26588476, 2015). "In Hyp/egr-1-/- mice which have chronically high circulating FGF23 concentrations, deletion of the egr-1 gene improves hypophosphatemia by 50% when compared to Hyp mice." (PMID 26588476, 2015). "We have shown that ERK1/2 signaling blockade suppresses renal egr-1 gene expression and prevents FGF23-induced hypophosphatemia and 1,25-dihydroxyvitamin D (1,25(OH)2D) suppression in mice." (PMID 26588476, 2015).
hypothyroidism (1 paper, 2016). Abnormally low levels of thyroid hormone. "Furthermore, our data provide candidate molecular mechanisms (deregulated expression of Bcl2, Zfp36l2, Egr1 and Hmga1) for the pesticides-induced hypothyroidism." (PMID 27905518, 2016).
Intellectual disability (1 paper, 2024). "However, a truncating mutation in the EGR1 gene has previously been proposed to play a pathogenic role in intellectual disability (c.1347_1348insA)." (PMID 35980567, 2024).
intestinal cancer (1 paper, 2019). "In intestinal cancer cells, early growth response protein 1 (EGR1), an important transcription factor that controls the expression of chemokines/cytokines involved in tumor metastasis such as CCL2 and CXCL1, is positively regulated upon activation of PERK and ATF6." (PMID 31064137, 2019).
Iron deficiency (1 paper, 2023). "Iron deficiency can independently modulate glycolysis, regulate genes involved in cholesterol and lipid metabolism, and increase Egr-1 signaling." (PMID 36829800, 2023).
ischemic heart diseases (1 paper, 2024). "The study suggests that treatment with miR-124-3p targeting EGR1 could be a potential novel therapeutic approach for cardioprotection in ischemic heart diseases in the future." (PMID 38926457, 2024).
leukopenia (1 paper, 2023). "We also analyzed the integrated results of metabolomics and transcriptomics and found that MDBD could relieve leukopenia and alleviate bone marrow damage by targeting steroid biosynthesis and IL-17 signaling pathway, in which the key genes are Jun, Cxcl2 and Egr1." (PMID 37601071, 2023).
Lewis lung carcinoma (1 paper, 2009). "To assess the rate of tumor growth in Egr-1-/- mice, we introduced 106 Lewis lung carcinoma cells (LLC1) subcutaneously in the flank of wild type and knockout animals." (PMID 19200397, 2009). "We injected 106 Lewis lung carcinoma (LLC1) cells subcutaneously in the flank of wild type and Egr-1 knockout mice." (PMID 19200397, 2009).
lipid metabolic disorders (1 paper, 2023). "With age increased, Egr-1 rhythm alteration might result in the uncoupling of Egr-1 with both circadian genes BMAL1/CLOCK and lipid metabolic genes Cidea, which results in the decoupling of liver circadian and lipid metabolic disorders in ageing mice." (PMID 36964140, 2023).
lipidosis (1 paper, 2017). "Moreover, adipocytokines IL6 and Leptin, in addition the genes, EGR1, FOS, SERPINE1, AGT and MMP2 might have great impacts on adipocyte differentiation and lipidosis." (PMID 28706200, 2017).
liver diseases (1 paper, 2017). "Extensive research has been conducted in animal models to elucidate Egr1 function in various liver diseases." (PMID 29607419, 2017).
lupus nephritis (1 paper, 2024). Glomerulonephritis in the context of systemic lupus erythematosus. "In the comparison of 62 subgroups, the up-regulated gene (PTPRC, MX1) and the down-regulated DEGs (EGR1, MME, RORC, ZBTB16, FKBP5) were verified to have mostly consistent change trends in all Lupus Nephritis vs. Normal Kidneys group with the results of GSE200306." (PMID 39301055, 2024). "Even though MX1, EGR1 and RORC were tested to be DEGs in the glomeruli and tubulointerstitium of primary lupus nephritis patients, in MRL/lpr mice, the difference was not being detected differentially." (PMID 39301055, 2024).
male infertility (1 paper, 2017). The inability of the male to effect fertilization of an ovum after a specified period of unprotected intercourse. "Nevertheless, further studies are required to validate whether these variants affect EGR4 gene function and increase the risk of male infertility associated with other genetic changes, such as EGR1 mutations." (PMID 28464846, 2017).
malignant glioma (1 paper, 2019). A grade III or grade IV glioma arising from the central nervous system. "Since ERG expression like cFos and EGR1 has been reported to correlate with radioresistance and poor prognosis in malignant glioma, we wondered if NMDAR signaling was also capable of regulating Top2β-dependent cFos expression in GBM cells." (PMID 30841565, 2019).
meningitis (1 paper, 2024). A disorder characterized by acute inflammation of the meninges of the brain and/or spinal cord. "Collectively, these findings provide support for the significant suppression of meningitis-induced production of proinflammatory cytokines and adhesion molecules, as well as improved survival resulting from Egr-1 deficiency." (PMID 38233877, 2024). "In this study, we demonstrate that the disruption of the BBB induced by meningitic E. coli is facilitated by the host transcription factor Egr-1, and we identify Egr-1 as a potential target for intervention in cases of E. coli meningitis." (PMID 38233877, 2024).
mesenchymal neoplasm (1 paper, 2026). "PURPOSE: Solitary fibrous tumour (SFT) is a rare mesenchymal neoplasm molecularly defined by the NAB2::STAT6 gene fusion (GF), an aberrant transcriptional regulator whose functions beyond EGR1 activation remain incompletely understood." (PMID 41665771, 2026).
metastatic cancer (1 paper, 2019). A carcinoma which has spread from the original site of growth to another anatomic site. "Our results show that overexpression of Oct4 increased metastatic lung nodules, whereas knockdown of Egr1 dramatically reduced metastatic lung nodules in an experimental metastatic cancer model." (PMID 31399076, 2019).
monocytic leukemia (1 paper, 2012). "For example, in response to LPS, ERK1/2-activated Elk-1, along with serum response factor (SRF), bind and activate the Egr1 promoter in THP-1 human monocytic leukemia cells." (PMID 23248776, 2012).
muscular dystrophy (1 paper, 2017). Muscular dystrophy (MD) refers to a group of more than 30 genetic diseases characterized by progressive weakness and degeneration of the skeletal muscles that control movement. "A mouse model associated with muscular dystrophy known as mdx mice display endplate reorganization similar to that of Egr-1−/− mice, with an increase endplate number, area, and area of the nerve." (PMID 28824419, 2017).
myxoid liposarcoma (1 paper, 2015). A liposarcoma characterized by the presence of round non-lipogenic primitive mesenchymal cells and small signet ring lipoblasts within a myxoid stoma with a branching vascular pattern. "By analogy with myxoid liposarcoma, we can hypothesize that trabectedin interferes with the physical interaction of the NAB2–STAT6 fusion protein with EGR1 to ensure its specific anti-tumor activity in SFTs." (PMID 26472661, 2015).
Neurodegeneration (1 paper, 2016). Progressive loss of neural cells and tissue. "Other than the potential candidate genes, the compact SPNW also included many significant connecting proteins like APP, BACE1, CCNA2, CREB1, E2F1, EGR1 and MDM2 which were previously implicated to play critical roles in many neurodegeneration disease pathogenesis including Alzheimer’s." (PMID 26784894, 2016).
oral diseases (1 paper, 2022). "Moreover, some studies revealed that miR-181a and Egr1 are involved in various oral diseases." (PMID 35890132, 2022).
papillary urothelial neoplasm (1 paper, 2009). "The high grade tumors showed significantly higher levels of Egr-1 positive tumor cells compared to low grade tumors or PUNLMP (papillary urothelial neoplasm of low malignant potential) (P < 0.001, Kruskal-Walis test)." (PMID 19878561, 2009).
peripheral vascular disease (1 paper, 2019). Any disorder affecting blood flow through the veins or arteries outside of the heart. "As current treatments for peripheral vascular diseases in humans are limited in effectiveness, this JNK3–Foxo3a–Egr1/Creb1 pathway may serve as a promising target for therapies aiming to improve the peripheral vasculature in diabetic and other affected patient populations." (PMID 31530804, 2019).
pheochromocytoma (1 paper, 2021). "Furthermore, our previous study reported that neurotrophic growth factors such as nerve growth factor induce neuronal differentiation in rat pheochromocytoma cells through ERK and EGR1 activation, associated with p35/CDK5 activation." (PMID 34207842, 2021).
pneumococcal infection (1 paper, 2014). Infections with bacteria of the species streptococcus pneumoniae. "Another example of an Acta2-regulating gene was the early growth response factor 1 (Egr1), up-regulated only by BALB/c during pneumococcal infection." (PMID 24594938, 2014).
primary aldosteronism (1 paper, 2025). An endocrine disorder characterized by excessive production of aldosterone by the adrenal glands. "Using RNA sequencing of RSL3-treated human adrenal cells and spatial transcriptomics of adrenal glands from patients with primary aldosteronism, we identify EGR1 as a key gene associated with RSL3-related oxidative stress and APAs." (PMID 39826326, 2025).
primary immunodeficiency (1 paper, 2022). "NK(EGR1) is upregulated in primary immunodeficiency, which in turn is associated with tumourigenesis in several cancers." (PMID 36046723, 2022).
promyelocytic leukemia (1 paper, 2018). "In support of this, HTyr has been shown to induce the expression of EGR1 in human promyelocytic leukemia cultured cells and, the oral administration of sulforaphane or SFGluc promoted the appearance of derived metabolites and the induction of HMOX1 in the breast tissue of rats and women." (PMID 29932449, 2018).
prostatic intraepithelial neoplasia (1 paper, 2013). "Egr1-null mice that were crossbred with either cancer model showed delayed progression from prostatic intraepithelial neoplasia (PIN) to invasive carcinoma." (PMID 23342084, 2013).
Renal cyst (1 paper, 2025). A fluid filled sac in the kidney. "We found the high expression and nuclear condensates of EGR1 in human ADPKD renal cyst epithelial cells and PKD mouse kidney tissue." (PMID 41810077, 2025).
retinoschisis (1 paper, 2022). An inherited or acquired disorder characterized by splitting of the retina into two layers. "As such, Egr1 levels were found to be differentially regulated by diverse forms of retinal stress and injury including photoreceptor degeneration in rd1 and rds mice, in retinoschisis and after optic nerve crush in rats." (PMID 35413909, 2022).
rheumatic disease (1 paper, 2023). "Iguratimod is a synthesized anti-rheumatic disease-modifying drug, which shows drastic inhibition to EGR1 expression in B cells." (PMID 37596660, 2023).
rhinosinusitis (1 paper, 2011). "However, expression profiling revealed only a tendency for reduced expression of EGR-1 mRNA in NP in comparison to the levels in rhinosinusitis without polyps, possibly “masked” by those cell types in NP tissue with steady or increased EGR-1 expression." (PMID 21984922, 2011).
rotator cuff tears (1 paper, 2022). "For example, MYL6B has been proved that it can differentially expressed in patients with rotator cuff tears, while EGR1 is conducive to the repair of rotator cuff tears." (PMID 36111133, 2022).
silicosis (1 paper, 2013). Silicosis is a respiratory disease caused by breathing in (inhaling) silica dust. "In accord with their study, our group(unpublished data) also found the augmented expression of Egr-1 in lung tissues from silicosis of animal model, and mainly located in pulmonary epithelial cells and macrophages." (PMID 23874821, 2013). "We also found comparable expression egr-1 and TGFβprotein in lung epithelial cells in rat model of silicosis." (PMID 23874821, 2013). "This study raises the possibility that blocking excessive Egr-1 signaling might be a potential therapeutic strategy to control silicosis related disease." (PMID 23874821, 2013). "Many studies found silica induced cell apoptosis, and recent studies demonstrated that Egr-1 took part in regulating cell apoptosis, but whether activated Egr-1 plays an important role in silicosis by affecting cell apoptosis need further study to elucidate." (PMID 23874821, 2013). "Our study has shown elevated Egr-1 expression in silicosis in vivo (unpublished data), which indicated Egr-1 might be one of the essential factors during the pathogenesis of silicosis." (PMID 23874821, 2013). "So increasing evidence indicates Egr-1 is the key regulator in the progression of silicosis." (PMID 23874821, 2013). "Our data demonstrated there was a pathway silica-ERK1/2, P38 MAPKs -Egr-1 in lung epithelial cells which might play a significant role in the pathogenesis of silicosis." (PMID 23874821, 2013). "Taken together, the activated Egr-1 might influence the progression of silicosis by TGFβ." (PMID 23874821, 2013).
small cell lung carcinoma (1 paper, 2016). Small cell lung cancer (SCLC) is a highly aggressive malignant neoplasm, accounting for 10-15% of lung cancer cases, characterized byrapid growth, and early metastasis. "Decreasing the expression of FGF2/EGR-1 pathway may also become an effective method to reduce the angiogenesis and vascular motion in small cell lung cancer." (PMID 26901069, 2016).
small intestinal NETs (1 paper, 2014). "Because miR-129-5p targets both G3BP1 and EGR1 we propose, that miR-129-5p is an important regulator of oncogenic signals in small intestinal NETs." (PMID 25546138, 2014).
solitary fibrous tumor (1 paper, 2025). Solitary fibrous tumor (SFT) represents a diverse group of ubiquitous rare spindle cell neoplasms that may be benign or malignant and that most frequently arises from the pleura and peritoneum and rarely from other sites such as head and neck, liver and skeletal muscle. "The solitary fibrous tumor (SFT) gene signature resembles EGR1-activated tumors." (PMID 40875449, 2025). "To validate our U2OS model of NAB2-STAT6 as a robust activator of certain EGR1 targets, we set out to determine genome-wide NAB2-STAT6 occupancy in a primary solitary fibrous tumor." (PMID 40875449, 2025).
synucleinopathy (1 paper, 2025). A neurodegenerative disease that is characterized by the abnormal accumulation of aggregates of alpha-synuclein protein in neurons, nerve fibers or glial cells. "Instead, we demonstrated the suppression of other microglial mobility/phagocytosis-associated genes such as Icam2, Acta2, Fos, Fosb, Egr1, Lamb2 and Tpm2 in both synucleinopathy patients and the animal model." (PMID 41258081, 2025).
testicular germ cell tumor (1 paper, 2026). A germ cell tumor arising from the testis.
thymic lymphoma (1 paper, 2019). "Further, EGF-dependent EGR1 upregulation inhibits the growth of thymic lymphoma by suppressing MMP9 production from stromal cells." (PMID 30845713, 2019).
ureteric obstruction (1 paper, 2010). "In addition, the early growth response gene 1 (EGR-1) has been implicated in the TGFβ-mediated fibrosis and in the regulation of interstitial fibrosis in the experimental unilateral ureteric obstruction model." (PMID 20976140, 2010).
vitiligo (1 paper, 2025). Generalized well circumscribed patches of leukoderma that are generally distributed over symmetric body locations and is due to autoimmune destruction of melanocytes. "Our analysis revealed dynamic alterations and functional roles of KLRC2+ NK cells, Treg cells, FCGR3A+ Cytotoxic CD8 + T cells, and EGR1+ B cells, opening new avenues for systemic immunology-oriented research in vitiligo." (PMID 41438750, 2025). "However, the reduction in EGR1 cell subpopulations and their functional characteristics in patients with vitiligo require further investigation and characterization." (PMID 41438750, 2025).
Yersinia infection (1 paper, 2016). "To investigate the effect of Ysr170 on host immune response to Yersinia infection, we examined TNF-α, IL-8, and transcription factor EGR1 expression in THP-1 cells infected with wild-type and Ysr170 KD strains." (PMID 28030576, 2016).